RABEP2 (rabaptin, RAB GTPase binding effector protein 2)
Description:
Plays a role in membrane trafficking and in homotypic early endosome fusion. Participates in arteriogenesis by regulating vascular endothelial growth factor receptor 2/VEGFR2 cell surface expression and endosomal trafficking. By interacting with SDCCAG8, localizes to centrosomes and plays a critical role in ciliogenesis.
Synonyms: FRA; FLJ23282
Tractability: PROTAC: ubiquitination databases record sites on it; its protein half-life has been measured.
Gene: Protein-coding gene on chromosome 16 (28,904,420 to 28,936,526, reverse strand). Ensembl gene ENSG00000177548.
Subcellular location: Cytoplasm; Early endosome; Cytoplasm, cytoskeleton, microtubule organizing center, centrosome; Cytoplasm, cytoskeleton, cilium basal body
Subcellular location (Human Protein Atlas): Cytosol; Golgi apparatus; Vesicles
Gene Ontology:
Molecular function: protein binding; growth factor activity; GTPase activator activity
Biological process: regulation of cilium assembly; endocytosis; signal transduction
Cellular component: centrosome; ciliary basal body; cytoplasm; cytosol; early endosome
Genetic constraint (gnomAD): Loss-of-function variants: 57 observed, 69.61 expected, observed/expected ratio (o/e) 0.82, 90% interval 0.66 to 1.02. The upper end of that interval is the gene's LOEUF score, 1.02, which puts it in group 4 of 6, group 1 being the genes least tolerant of losing a copy. Missense variants: 691 observed, 744.25 expected, observed/expected ratio (o/e) 0.93, 90% interval 0.87 to 0.99. Synonymous variants: 351 observed, 336.09 expected, observed/expected ratio (o/e) 1.04, 90% interval 0.96 to 1.14.
Homologues: Orthologues: dog RABEP2 (91% identical), macaque RABEP2 (89% identical), pig RABEP2 (89% identical), guinea pig RABEP2 (86% identical), mouse Rabep2 (83% identical), rat Rabep2 (83% identical), rabbit RABEP2 (78% identical), chimpanzee RABEP2 (76% identical), zebrafish rabep2 (29% identical), Caenorhabditis elegans rabn-5 (15% identical). Paralogues in human: RABEP1 (38% identical).
Diseases named in the same sentence as RABEP2 in open-access papers:
RABEP2 is named in the same sentence as 7 diseases in open-access papers, as found by Europe PMC text mining. Sharing a sentence is not in itself a finding about the gene and the disease. The quoted sentences say what the papers report.
Stroke (2 papers, 2017 to 2023). Sudden impairment of blood flow to a part of the brain due to occlusion or rupture of an artery to the brain. "Further, hypoxia increases the expression of Vegf, Hif2α, and Rabep2 (the gene that underlies differential mouse strain vulnerability in stroke) and induces de-novo formation of cerebral collaterals." (PMID 37822524, 2023).
ischemic stroke (1 paper, 2023). A stroke disorder caused by obstruction of blood flow to the brain, due to thrombotic (local blood clot formation) or embolic (due to a blood clot or other material traveling from another site) event. "The results indicated that both mouse and human RABEP2 could rescue the ischemic stroke volume and collateral vessel phenotype in Rabep2 KO mice, while human RABEP2‐coding mutations significantly impaired the rescue of collateral vessel density and infarct volume phenotypes." (PMID 37551863, 2023).
morbid obesity (1 paper, 2021). An excess of body weight, normally defined as an individual with a body mass index greater than 35 or a body weight greater than one hundred percent of ideal body weight. "2, TUFM, SH2B1, ATP2A1-AS1, and RABEP2) located in the 16p11.2 region, SH2B1 was reported as the causal gene of morbid obesity." (PMID 34529725, 2021).
tumor (1 paper, 2022). "RABEP2 is a recently identified protein required for the formation of collateral vessels during development, which is possibly why it can promote the development of an ESCC tumor." (PMID 35497331, 2022).
RABEP2 also shares sentences with these, for which no sentence is quoted: breast carcinoma (1 paper); cardiac ischemia (1); Obesity (1).